DOP1A (DOP1 leucine zipper like protein A)
Description:
May be involved in protein traffic between late Golgi and early endosomes.
Synonyms: DOPEY1; KIAA1117; dJ202D23.2; DOP1
Tractability: Antibody: UniProt places it where antibodies can reach, with medium confidence. PROTAC: ubiquitination databases record sites on it.
Gene: Protein-coding gene on chromosome 6 (83,067,666 to 83,171,350, forward strand). Ensembl gene ENSG00000083097.
Subcellular location: Golgi apparatus membrane
Subcellular location (Human Protein Atlas): Nucleoplasm; Vesicles
Gene Ontology:
Molecular function: protein binding
Biological process: Golgi to endosome transport
Cellular component: Golgi apparatus; endolysosome; endoplasmic reticulum; endosome; Golgi membrane; trans-Golgi network; cytosol
Genetic constraint (gnomAD): Loss-of-function variants: 76 observed, 233.08 expected, observed/expected ratio (o/e) 0.33, 90% interval 0.27 to 0.4. The upper end of that interval is the gene's LOEUF score, 0.4, which puts it in group 1 of 6, group 1 being the genes least tolerant of losing a copy. Missense variants: 2,284 observed, 2,820.6 expected, observed/expected ratio (o/e) 0.81, 90% interval 0.78 to 0.84. Synonymous variants: 876 observed, 980.48 expected, observed/expected ratio (o/e) 0.89, 90% interval 0.84 to 0.94.
Homologues: Orthologues: chimpanzee DOP1A (99% identical), macaque DOP1A (99% identical), dog DOP1A (96% identical), pig DOP1A (95% identical), guinea pig DOP1A (94% identical), mouse Dop1a (93% identical), rat Dop1a (93% identical), rabbit DOP1A (92% identical), tropical clawed frog dop1a (81% identical), zebrafish dop1a (71% identical), Drosophila melanogaster CG15099 (30% identical), Caenorhabditis elegans pad-1 (26% identical). Paralogues in human: DOP1B (37% identical).
Diseases named in the same sentence as DOP1A in open-access papers:
DOP1A is named in the same sentence as 5 diseases in open-access papers, as found by Europe PMC text mining. Sharing a sentence is not in itself a finding about the gene and the disease. The quoted sentences say what the papers report.
Ataxia (1 paper, 2024). Ataxia refers to impaired coordination of voluntary muscle movement. "Consistently, the recovery of tremors and the decreasing of periaxonal vacuoles in the dop1a-null-mutant rats, as well as the recovery of nystagmus/ataxia in IV-2, both indicated that there might be other pathways that could complement the dysmyelinogenesis of PLP/MAG partially in adulthood." (PMID 38818041, 2024).
neurodevelopmental disorder (1 paper, 2024). A behavioral and cognitive disorder with onset during the developmental period that involves impaired or aberrant development of intellectual, motor, or social functions. "There has been strong evidence that dop1a null mutations cause abnormal myelinogenesis, and myelinogenesis is universally considered the primary cause of many neurodevelopmental disorders." (PMID 38818041, 2024). "This further supports the perspective that disorganized myelinogenesis due to congenital DOP1A deficiency might cause neurodevelopmental disorders (NDDs)." (PMID 38818041, 2024).
DOP1A also shares sentences with these, for which no sentence is quoted: neurodevelopmental disabilities (1 paper); Nystagmus (1); prostate carcinoma (1).